MMP9 (matrix metallopeptidase 9)
Diseases named in the same sentence as MMP9 in open-access papers (continued):
Sharing a sentence is not in itself a finding about the gene and the disease.
kidney disease (49 papers, 2009 to 2025). "The upregulation of MMP9 expression is associated with many kidney diseases, and the degree and duration of its expression could affect the extent of kidney injury." (PMID 37144215, 2023). "In human diseases, however, elevated MMP-9 has been reported in many autoimmune diseases, such as rheumatoid arthritis, multiple sclerosis, and kidney diseases." (PMID 41341833, 2025). "The level of circulating MMP-9 varies in patients with different kidney diseases, and even in the context of the same disease its level is controversial in several publications." (PMID 41341833, 2025). "Urinary MMP-9 concentrations correlate with urea, creatinine, glomerular filtrations rate, and proteinuria in renal disease in humans." (PMID 38136813, 2023). "The systemic activation of MMP-9 is a marker of a lasting inflammatory state that is inherent to renal disease, as has been demonstrated even with adequate pharmacological treatment in patients with CKD." (PMID 32225016, 2020). "The results demonstrate that the appearance of NGAL monomer and MMP-9 monomer are both significantly associated with elevated levels of serum BUN, creatinine and phosphate, which are known to be linked with renal disease." (PMID 31455336, 2019). "Several reports indicate that MMP-2 and MMP-9, which are expressed in glomerular injury, control extracellular matrix turnover in kidney disease states." (PMID 29461477, 2018). "While there are several reports of MMP-9 in kidney diseases, as a function of the subjects included, the methodology employed and the fluid analyzed (urine), there are few with which we can compare our findings." (PMID 30564523, 2018). "The activity of MMP-9 is controlled by TIMP-1, and both members of the MMP-9–TIMP-1 tandem are implicated in several disease states including cardiovascular and renal disease." (PMID 28791014, 2017). "have indicated increased serum MMP-9 concentrations in immunoglobulin A nephropathy and other nephropathies." (PMID 28494217, 2017). "Early combination therapy with inhibitors of Mmp2, Mmp3 and Mmp9 significantly delayed the onset of proteinuria, while treatment after onset of proteinuria accelerated renal disease." (PMID 26673451, 2015). "Little is known about MMP-9 measurements in horses and its use as a marker of renal disease." (PMID 38136813, 2023). "Moreover, previous studies indicate that MMP-2 and MMP-9 are overexpressed in the glomerulus in kidney disease states." (PMID 29461477, 2018). "Plasma and urine concentrations of MMP-9 and IL-8 have been examined in various kidney diseases." (PMID 28494217, 2017). "However, until now, studies that evaluated the use of MMP-9 as a biomarker to detect renal disease are rare, and its use as such is largely unknown." (PMID 38136813, 2023). "Secretion of TNF, CSF2, MMP9, CTGF and PAI-1 were measured, as these molecules are known to modulate kidney disease progression in various animal models of CKD." (PMID 39005931, 2024). "The markers reflecting turnover of COL III (C3M) and LAMC1 (LG1M) measured in our study are both generated by matrix metalloproteinase-9 (MMP-9), a protease known to have a temporal and spatial expression during renal disease progression." (PMID 32824113, 2020). "A majority of studies in patients with kidney diseases as well as animal models hereof demonstrate that the renal content of MMP‐2 and MMP‐9 are increased." (PMID 24744860, 2013). "For example, MMP-9 and MMP-2 have been elevated in various kidney disease models and humans, and urinary TIMP-1 has already been proposed as a marker of kidney function in patients after kidney transplantation and also its expressions have been increased in patients with CKD." (PMID 35205098, 2022). "The authors believe that the current available literature on MMP-9 does not allow to make statements about its potential as a biomarker for kidney disease." (PMID 36230418, 2022).
kidney disease (continued). "Literature on MMP-9 does not allow for conclusive statements about its potential as a biomarker for kidney disease." (PMID 36230418, 2022). "While the NGAL monomer has been associated with tubular injury, and neutrophils seem the main source of NGAL dimer in urine, the complex of MMP 9 (gelatinase B) with NGAL has not been extensively studied in the context of kidney diseases." (PMID 33375581, 2020). "Earlier studies found that deletion of MMP-9 in Alport mice did not influence renal disease progression, suggesting that MMP-9 may not contribute significantly to the pathology." (PMID 24915008, 2014).
adenocarcinoma (42 papers, 2008 to 2025). A common cancer characterized by the presence of malignant glandular cells. "MMP-9 was significantly associated with both disease-free survival and OS just in adenocarcinoma group." (PMID 32944046, 2020). "In addition, MMP-9 was significantly associated with both disease-free survival and OS in the adenocarcinoma group." (PMID 38558822, 2024). "We demonstrated that levetiracetam can inhibit MC degranulation and, in particular, the release of MMP9, thus restraining the pro-adenocarcinoma activity of MCs in TRAMP mice." (PMID 37376140, 2023). "Again, a correlation between the level of MMP9 gene expression and the length of survival of patients with adenocarcinoma was confirmed." (PMID 37509417, 2023). "A study conducted on adenocarcinoma cells demonstrated that the HS chains of glypicans interact with matrix metalloproteinase-9 (MMP-9), playing a pivotal role in cell motility." (PMID 36142190, 2022). "In mice bearing subcutaneous tumors levetiracetam was partially active on both NEPC and adenocarcinoma, the latter effect due to the inhibition of MMP9 release by MCs." (PMID 33737929, 2021). "There was also a significant positive correlation between IL-6 and MMP-9 in adenocarcinoma and SqCC, with correlation coefficients of 0.53 and 0.49, respectively." (PMID 34439874, 2021). "Particularly intriguing is the correlation between IL-6 and MMP-9 in patients with adenocarcinoma and SqCC, with correlation coefficients of 0.53, 0.49, respectively, which undoubtedly influences TME processes." (PMID 34439874, 2021). "The pairwise correlation revealed a significant positive correlation between IL-6 and MMP-9 in adenocarcinoma and SqCC, with correlation coefficients of 0.53 and 0.49, respectively." (PMID 34439874, 2021). "For example, a soya bean BBI can suppress MMP‐2 and MMP‐9 enzyme activity to inhibit the growth of the two adenocarcinoma cells AGS and HT29." (PMID 32415911, 2020). "It has been reported that DDP treatment suppressed the MMP2 and MMP9 protein expressions significantly in human adenocarcinoma cell line A549." (PMID 33329003, 2020). "The mast cells in the TME produce MMP-9 that enhanced the outgrowth of well-differentiated adenocarcinoma cells by promoting angiogenesis, EMT and invasion." (PMID 31547070, 2019). "Poorly differentiated adenocarcinoma produces MMP-9 autocrinously, thus becoming independent from mast cells." (PMID 25699233, 2015). "MMP-9 produced by mast cells within the tumor microenvironment enables well-differentiated adenocarcinoma outgrowth by favoring angiogenesis and invasion to the surrounding tissue in TRAMP mice." (PMID 25699233, 2015). "Single nucleotide polymorphisms (SNPs) at four TIMP (TIMP1-4) and three MMP genes (MMP2, MMP7 and MMP9) were genotyped in DNA samples from a prospective cohort of patients with primary adenocarcinoma of the GEJ admitted to the British Columbia Cancer Agency." (PMID 23527119, 2013). "The increase of mean serum levels of MMP-9 was statistically significant in stage III adenocarcinoma patients and was also found to be significantly correlated with increased serum levels of IL-8 of CRC at stage III." (PMID 22848630, 2012). "Serum levels of IL-8 in adenocarcinoma patients were increased from stage II, when also the enzymatic activity of MMP-9 increased." (PMID 22848630, 2012). "Furthermore, microenvironment changes including endogenous IL-6 expression, MMP-9 production and other pro-inflammation cytokines upregulation fulfil complicated and comprehensive function in the process of adenocarcinoma transdifferentiating into NEC." (PMID 34956090, 2021). "Immunohistochemical MMP-9 expression in NSCLC (both adenocarcinoma and SCC) could be a significant prognostic factor." (PMID 32944046, 2020). "Additionally, in comparison with normal samples, the expression level of CCR7, CXCL10, IDO1, and MMP9 were increased in phases of adenocarcinoma’s tissue, while the expression level of CXCL9 and VCAM1 were decreased." (PMID 31214045, 2019).
adenocarcinoma (continued). "Significant relationship existed between MMP9 activity level and adenocarcinoma subtypes." (PMID 27456862, 2016). "Although the invasive property was shown to be related to TGase 2 expression in squamous NSCLC cell lines via the regulation of MMP-9 in the present study, the reason that TGase 2 expression has an impact on survival or recurrence only in the non-adenocarcinoma subtype remains to be revealed." (PMID 21943122, 2011). "However, there is evidence that prognostic value of MMP-9 may be of more importance in adenocarcinoma than in SCC." (PMID 38558822, 2024). "IHC analysis revealed that MMP-9 expression was significantly higher in advanced-stage tumors, in SCC compared to adenocarcinoma, in patients with positive lymph node involvement, and in those with brain metastases (all p ≤ 0.05)." (PMID 40321254, 2025). "After 24 h on a 3D RPM, the migration-related genes MMP-2, MMP-9, TIMP-1, and TIMP-2 were all upregulated both in a squamous (H1703) and in an adenocarcinoma (A549) cell line." (PMID 37048115, 2023). "In vitro experiments using the adenocarcinoma cell lines A549 and H1299 and the squamous cell line, SK-MES-1 demonstrated that KLHL38 promotes migration and invasion by upregulating RhoA and MMP9 and downregulating E-cadherin." (PMID 34050138, 2021). "The expressions of MMP-9 and MMP-16 have shown a statistical relationship with the villous histological type in comparison to NOS adenocarcinoma." (PMID 32813775, 2020). "MMP-9 and MMP-16 show greater expression with villous histological type versus NOS adenocarcinoma (p = 0.01 and fold change of 1.13 and p = 0.03 and fold change of 1.61)." (PMID 32813775, 2020). "In our study, MMP-9 expression was significantly more frequent in relation to the villous histological type, which has a better prognosis than NOS adenocarcinoma." (PMID 32813775, 2020). "When adenocarcinoma A549 cells were exposed to the microgravity environment, MMP-2, MMP-9, TIMP-1, and TIMP-2 showed higher expression in the MG than in the CONT at 24 h." (PMID 31601869, 2019). "Aconitine has effects on inhibiting cell proliferation invasion and metastasis of human adenocarcinoma A549 cell lines through decreasing the expression of MMP-2 and MMP-9 activity." (PMID 29234363, 2017). "Patient 1, who had stage I adenocarcinoma with high PAI-2 and low MMP-9 IHC expression levels, was alive at the final follow up." (PMID 26230665, 2015). "Within the -1562CC genotype, we observed the highest MMP-9 concentration in the adenocarcinoma patients (x ̄ = 959.95 ng/mL) and the lowest in the non-smoking controls (x ̄ = 358.74 ng/mL)." (PMID 37445754, 2023). "The distribution of adenocarcinoma and SCC were even in MMP-9 expression score groups." (PMID 32944046, 2020). "In this study, MMP-9 expression appeared significantly more frequently in the villous histological type that, according to the literature studies, shows a better prognosis than SOE adenocarcinomas." (PMID 24737953, 2014). "Interestingly, MMP-9 and pro-MMP-9 are notably elevated in serum-derived exosomes from patients with EGFR-mutated adenocarcinoma, and this is independent of stage, gender, age, or smoking history." (PMID 35954442, 2022). "We did not analyze MMP-9 expression distinctly in adenocarcinoma and SCC subgroups." (PMID 32944046, 2020). "The authors observed that MMP-9 was a poor prognostic factor only for adenocarcinoma, not SCC." (PMID 32944046, 2020). "However, there is evidence that prognostic value of MMP-9 may be of more importance in adenocarcinoma and not in SCC." (PMID 32944046, 2020). "For instance, a previous study showed that MMP-9 expression, observed in 38.6% of resected NSCLC specimens, was significantly correlated with poor survival and recurrence only among adenocarcinoma tumors, but not in SCC group." (PMID 32944046, 2020).
neurodegenerative disease (37 papers, 2011 to 2025). A disorder of the central nervous system characterized by gradual and progressive loss of neural tissue and neurologic function. "In conclusion, in the case of neurodegenerative diseases, it is difficult to determine which allele or genotype in the MMP-9-1562C/T polymorphism is associated with a higher probability of developing the diseases." (PMID 37206663, 2023). "Overproduction of MMP-9 from these phagocytes and microglia has been implicated in the pathogenesis of several notable neurodegenerative diseases." (PMID 29849502, 2018). "Furthermore, MMP-9 is implicated in the clearance of various misfolded proteins involved in several neurodegenerative diseases, such as Aβ." (PMID 34566627, 2021). "Multiple neurodegenerative diseases share MMP9 dysregulation, including ALS, where MMP9 has been shown to have a neurotoxic effect." (PMID 40002468, 2025). "Many of these genes, such as MMP9 and CCL2, have been previously implicated in blood–brain barrier disruption, leukocyte migration, and cytokine signaling in neurodegenerative disease models." (PMID 41614741, 2025). "Chronic MMP-9 activity promotes aneurysm expansion by degrading elastin and weakening vascular walls, while in neurodegenerative diseases, sustained proteolysis disrupts the blood–brain barrier and exacerbates neuronal injury." (PMID 41304763, 2025). "Targeting MMP9 can reverse neuroinflammation and provide a new strategy for the treatment of neurodegenerative diseases." (PMID 40918113, 2025). "MMP-2 and MMP-9 are able to cleave Aβ monomers and oligomers, while MMP-9 is unique in its ability to also cleave Aβ fibrils and clear plaques from amyloid-laden brains, thus making MMPs potential targets for neurodegenerative diseases and in particular AD." (PMID 40869114, 2025). "Our ongoing research endeavors aim to dissect the specific interactions between BK, RTKs, and MMP-9, thereby providing comprehensive insights into the intricate signaling cascades at play in neurodegenerative diseases." (PMID 38137419, 2023). "Activated microglia and astrocytes are the main inducers of MMPs, including MMP-9 a chief element of the basement membrane that contributes to the onset and progression of neurodegenerative diseases, including PD." (PMID 36677744, 2023). "Studies have shown that cytokines released from neurons, including CCL2, CCL21, HMGB1, CGRP, Substance P, CX3CL1, MMP2, and MMP9, can mediate microglia activation in brain injury, neuropathic pain, or neurodegenerative diseases." (PMID 36131309, 2022). "Altered levels of MMP-2 (Gelatinase A) and MMP-9 (Gelatinase B), potentially contributing to disease pathogenesis, have been shown to be altered in several neurodegenerative diseases including AD, and ALS." (PMID 29459817, 2017). "Our previous study indicates that MMP-9 expression promotes pathological processes in brain injury, inflammation and neurodegenerative diseases." (PMID 29209167, 2017). "MMPs, namely gelatinases MMP-2 and MMP-9, contribute to the progression of chronic and degenerative diseases." (PMID 27589705, 2016). "Elevated levels of MMP-9 in the plasma and brain are associated with BBB disruption, leading to an exacerbation of neurodegenerative diseases." (PMID 21867555, 2011). "The present review synthesizes current evidence on how clinically approved drugs and investigational agents modulate MMP-9 expression and activity, aiming to point out therapeutic opportunities for state-specific regulation across inflammatory, fibrotic, vascular, and neurodegenerative diseases." (PMID 41304763, 2025). "In neurodegenerative diseases such as Alzheimer’s and Parkinson’s, persistent MMP-9 activity induces low-grade BBB leakage, facilitating accumulation of inflammatory mediators and neurotoxic proteins that exacerbate neuronal damage and accelerate disease progression." (PMID 41304763, 2025).
neurodegenerative disease (continued). "Finally, the upregulation of MMP-9 expression in brain astrocytes and its consequent enhancement of cell migration contribute to the development of neuroinflammation and neurodegenerative diseases, such as AD." (PMID 38275397, 2024). "Importantly, in neurodegenerative diseases, MMP9 has been similarly found to be a key determinant regulating the selective degeneration of neuronal cell types." (PMID 39635981, 2024). "In addition, increased Aβ was associated with increased levels of MMP9, which has been linked to BBB breakdown in neurodegenerative diseases, including AD." (PMID 33513818, 2021). "Thus, elevated activity and/or expression of iNOS, COX-2, MMP-9, IL-1β and TNF-α in brain cells have been implicated in the cascade of events leading to neurodegenerative diseases." (PMID 22018032, 2011). "MMP-9 especially may contribute to neurodegenerative diseases." (PMID 30562971, 2018). "Among MMPs, gelatinase-A (MMP-2) and gelatinase-B (MMP-9) are recognized as the key enzymes in the degradation of type IV collagen, the major component of basement membrane and are emerging as critically involved in chronic inflammatory and degenerative diseases." (PMID 27589705, 2016). "Conversely, E2 treatment increased active MMP-2 and MMP-9 in SH-SY5Y neuroblastoma cells, which model neurodegenerative diseases." (PMID 33758788, 2021). "On the other hand, in certain neurodegenerative diseases such as AD and MMPs, and, in particular, MMP-3 and MMP-9, were shown to degrade Aβ plaques, justifying the view of MMPs as a double-edged sword." (PMID 26538832, 2015). "More than a dozen MMPs were shown to be involved in neurodegenerative diseases, including MMP-2, MMP-3, and MMP-9, and they seem to be important players in most of the diseases mentioned in this review." (PMID 26538832, 2015). "Thus, COX-2, iNOS and MMP-9 activities, as well as TNFα, IL-1β and NO generation have become accepted as markers and therapeutic targets in neurodegenerative diseases, and thus their down-regulation might assist in preventing or delaying the onset of these diseases." (PMID 22018032, 2011). "The identified hub genes—particularly MMP9, CCL2, and S100A8/A9—may serve as promising candidates for therapeutic intervention or biomarker development across multiple neurodegenerative diseases." (PMID 41614741, 2025). "In contrast, genetic ablation of either MMP2 or MMP9, two major downstream targets of MT1-MMP linked to neurodegenerative diseases, did not alter memory functions in aged mice." (PMID 40983624, 2025). "The curcuminoids also mitigate iNOS, COX-2, TGF-β1/2, matrix metalloproteinase-9 (MMP-9), and brain-derived neurotrophic factor (BDNF) expression, attenuate α-synuclein aggregation, and generally, lessen the severity of the symptoms of neurodegenerative diseases." (PMID 35883772, 2022).